RN7SL790P (RNA, 7SL, cytoplasmic 790, pseudogene)
Gene: Miscellaneous RNA gene on chromosome X (74,390,692 to 74,390,989, forward strand). Ensembl gene ENSG00000239745.
Homologues: Orthologues: macaque Metazoa_SRP (94% identical). Paralogues in human: RN7SL1 (82% identical), RN7SL2 (82% identical), RN7SL3 (81% identical), RN7SL45P (81% identical), RN7SL566P (81% identical), RN7SL220P (80% identical), RN7SL478P (80% identical), RN7SL630P (80% identical), RN7SL126P (79% identical), RN7SL197P (79% identical), RN7SL278P (79% identical), RN7SL296P (79% identical), and 700 more.